IL10 (interleukin 10)
Diseases named in the same sentence as IL10 in open-access papers (continued):
Sharing a sentence is not in itself a finding about the gene and the disease.
ischemic stroke (continued). "Previous studies have suggested that activated CD8+ T lymphocytes inhibit neural stem/progenitor cell proliferation via interferon-gamma (IFN-γ) and that activated regulatory T cells increase neurogenesis through IL-10 and TGF-β after ischemic stroke." (PMID 34262436, 2021). "Here, we sought to examine the concentrations of inflammatory cytokines (IL-1β, IL-6, and IL-10) and growth factors (VEGF, BDNF/TrkB and TGF-β) 24-h and 30 days after ischemic stroke." (PMID 34408211, 2021). "Notably, STAT3 is a pivotal mediator of the anti-inflammatory effects of IL-10 also in human macrophages and is among the highly predicted target genes for the dysregulated miRNAs occurring in the peripheral blood mononuclear cells (PBMCs) of ischemic stroke patients." (PMID 31849581, 2019). "IL-10 and TGF-β are released by the anti-inflammatory cells, to promote recovery from ischemic stroke." (PMID 29896414, 2018). "Serum levels of CRP, IL-6, IL-10, and IL-23 were significantly correlated with lesion volume and/or NIHSS in patients with ischemic stroke." (PMID 27682880, 2017). "Both in vivo and in vitro ischemic stroke models induced the production of inflammatory mediators, including TNF-α, IL-1β, iNOS, and IL-10." (PMID 28592261, 2017). "However, it is unknown if sex differences exist in IL-10 levels after ischemic stroke." (PMID 26462256, 2015). "In conclusion, IL-10 levels ≥30 mg/mL increase the ability to identify salvageable brain tissue in patients with CDM and PDM and facilitates the selection of ischemic stroke patients for systemic thrombolysis." (PMID 23773291, 2013). "To investigate whether GJC-CDs are involved in the inflammatory response in ischemic stroke, we examined the levels of TNF-α, IL-1β, IL-6, and IL-10 in the serum of each group of mice." (PMID 40573265, 2025). "This suggests that the protective effect of intranasal BDNF in ischemic stroke might be partially due to the downregulation of TNF-α and the upregulation of IL-10." (PMID 40895108, 2025). "In clinical practice focusing on prognostic indicators for ischemic stroke patients found that there was a close negative correlation between IL-10 and NIHSS scores (P=0.0006), but not between IL-4 and NIHSS scores (P=0.088)." (PMID 40134421, 2025). "Proinflammatory cytokines such as IFN-gamma, IL-6, IL-10, and TGF-beta, which are increased due to ischemic stroke, might link the brain ischemia to endothelial dysfunction." (PMID 39311310, 2024). "In animal models of ischemic stroke, cytokines were upregulated, which triggered proinflammatory (e.g., interleukin [IL]-1β, tumor necrosis factor [TNF], and IL-6) and anti-inflammatory (transforming growth factor-β and IL-10) mechanisms." (PMID 38206990, 2024). "We hypothesized that optogenetic activation of astrocytic calcium-influx via ChR2 could release IL-10 to improve BBB integrity and subsequently reduce neuronal death during the acute phase of ischemic stroke." (PMID 37196130, 2023). "Current evidence suggests that IL-10 and transforming growth factor-β (TGF-β) are anti-inflammatory cytokines mainly produced by microglia, regulatory T cells, and astrocytes, which are required for sensory motor recovery after ischemic stroke." (PMID 34262436, 2021). "RACs produce anti-inflammatory responses through immune-mediators including IL-10 and VEGF, so RACs might reduce the infarct volume in post-ischemic stroke in humans, too." (PMID 30682162, 2019). "The MCAO challenge itself induced a significant up-regulation of pro- and anti-inflammatory genes in the brains of both control and treatment animals, including IL-6, IL-1β, TNF-α, IL-10, CCL2, and CCL3, indicating a pivotal role of neuroinflammation in the pathology of acute ischemic stroke events." (PMID 30126083, 2018). "Despite existing knowledge, the temporospatial expression and cellular sources of endogenous IL-10 and its receptor following ischemic stroke are still not known." (PMID 24499655, 2013).
ischemic stroke (continued). "Uni-variable analyses showed that the mean IL-10 was not significantly different between patients with ischemic stroke and controls." (PMID 24040186, 2013). "Model 1 containing IL-10 (yes/no top tertile) and SNPs scores significantly predicted the likelihood of ischemic stroke but with a modest AUC of 0.609 (95% CI 0.556-0.662, p<0.001)." (PMID 24040186, 2013). "Thus, IL-10 and TGF-β contribute to maintaining BBB structure and function in ischemic stroke." (PMID 34248961, 2021). "In addition, the prognostic value of IL-10 in ischemic stroke patients in another study was not confirmed." (PMID 34336007, 2021). "Summary of non-genetic IL-10 ischemic stroke clinical studies." (PMID 28659854, 2017). "In addition, the effects of rs1554286 and rs3021094, minor alleles that are 28.4% and 47.8% prevalent in Chinese, which are situated in the intron region of IL-10 gene, on serum IL-10 levels and ischemic stroke have not been previously reported." (PMID 24040186, 2013). "We showed that salivary TNF-α and IL-6 were significantly higher, whereas IL-10 content was statistically lower in both non-stimulated (NWS) and stimulated (SWS) whole saliva of ischemic stroke patients." (PMID 34433866, 2021).
pancreatic cancer (110 papers, 2010 to 2026). "Elevated levels of inflammatory-mediated cytokines such as IL-6 and IL-10 have been associated with poor prognosis in patients with pancreatic cancer." (PMID 38662232, 2024). "Elevated levels of IL-6 and IL-10 in the serum of pancreatic cancer patients have been associated with a poor prognosis." (PMID 37760608, 2023). "Serum levels of IL-6, IL-8, IL-10, and IL-1RA were significantly increased in pancreatic cancer patients and were associated with worse survival rates, poor performance status." (PMID 36899319, 2023). "Treg cells secrete inhibitory cytokines such as TCF-β, CTLA4, IL-10, and PD-L1 to mediate the immune tolerance of the effective cell to pancreatic cancer associated antigen, thereby avoiding the tumor cells from immune surveillance." (PMID 37064113, 2023). "In pancreatic cancer, studies showed that the presence of IL10 has been associated with poor prognosis." (PMID 37628994, 2023). "In pancreatic cancer, elevated serum IL-6 and IL-10 concentrations have been linked with worse prognosis, as has the pro-inflammatory cytokine IL-18." (PMID 35034144, 2022). "We aimed to assess the status of naturally occurring CD4+ and CD8+ T cell responses to a tumour associated antigen, Mesothelin, in patients with pancreatic carcinoma and study the effects of elevated IL-10 on Mesothelin-specific T cell responses." (PMID 24520352, 2014). "Finally, our analysis of inflammatory biomarkers shows that AIF-1, IL-12A and IL-18 are directly related to pancreatic cancer mortality, whereas IL-10 shows an inverse association." (PMID 38785507, 2024). "Additionally, IL-10 is linked with M2-polarized TAMs and their infiltration intensity correlates with pancreatic cancer prognosis." (PMID 39195299, 2024). "T-cells derived from CP patients responded towards pancreatitis-associated antigens, increasing IL-10-based responses; however, the T-cells obtained from pancreatic cancer patients responded towards pancreatic cancer-associated antigens, resulting in high IFN-γ levels." (PMID 32796685, 2020). "In pancreatic cancer, researchers have found that the KrasG12D mutation up-regulated the levels of interleukin-10 (IL-10) and transforming growth factor-β (TGF-β) through activating the MEK/ERK pathway inducing regulatory T cells (Tregs) conversion and immunosuppressive." (PMID 32874132, 2020). "In parallel, IL-10 has been associated with poor survival in pancreatic cancer." (PMID 27589570, 2016). "Levels of IL-6, IL-8, IL-10, and IL-23 were significantly associated with the direct number of circulating bone marrow (BM)-derived mesenchymal or very small embryonic/epiblast-like stem cells (SCs) in patients with pancreatic cancer." (PMID 24849506, 2014). "After measuring cytokine levels (IL-6, IL-8, IL-10, IL-23, TNFα) in this group, we added these patients to our analyses, constructed ROC curves, and determined the approximate AUC values to assess the suitability of these cytokines as diagnostic markers for pancreatic cancer." (PMID 24849506, 2014). "An IL-10-based Trikine induced immune infiltration into poorly immunogenic tumors, showing efficacy in preclinical models of small cell lung cancer and pancreatic cancer." (PMID 41712697, 2026). "In the immune evasion process of pancreatic cancer cells, inflammatory factors like IL-6, TNFα, and IL-10 have been found to be significantly involved." (PMID 40487760, 2025). "T cell response analysis in peripheral blood from CP patients, pancreatic cancer patients, and healthy individuals found that IL-10-specific responses in pancreatitis were mediated by IL-10+ IFN-γ- FoxP3+ regulatory T cells." (PMID 40959561, 2025). "CAFs, which can be triggered by fibroblast activation protein, alpha-smooth muscle actin, inflammation cytokines–IL-8, IL-10, and exosomes with miRNA, promote and accelerate new signalling pathway networks formation in pancreatic cancer cells." (PMID 39457656, 2024).
pancreatic cancer (continued). "Elevated levels of cytokines such as IFN-gamma, IL-6, IL-10, and TNF-alpha have been associated with an increased risk of pancreatic cancer." (PMID 39599705, 2024). "A recent study in pancreatic cancer shows that the increased invasion of TAM2s can promote the EMT process of pancreatic cancer by activating TLR4/IL-10 signaling pathway in cancer cells, reducing E-cadherin and increasing the expression of Vimentin." (PMID 38693304, 2024). "Clinical studies have shown IL-10 upregulation in pancreatic cancer and its correlation with tumor stage and prognosis." (PMID 39195299, 2024). "Pancreatic cancer cells escape immunity by secreting cytokines such as IL-10 and TGF-β, immunosuppression as a result of these cytokines affects the immune function by inhibiting the infiltration of CD4+ and CD8+ T cells in the cancer cells." (PMID 38973003, 2024). "IL-10 also through TLR4/IL-10 signaling pathway alter macrophages to TAM M2 to promote epithelial-mesenchymal transition in pancreatic cancer cells." (PMID 36816959, 2023). "Pancreatic cancer cells secret of various cytokines (such as IL-10, TGF-B and IL-23) and chemokines (such as CXCL1-3, CXCL5, CXCL12, CCI2 and VEGF) to enhance the activation of stromal cells and the accumulation of immunosuppressive cells." (PMID 37064113, 2023). "Herein we prove that several pancreatic cancer cell lines induce myeloid suppressor cell phenotypes through production of IL-10." (PMID 36310582, 2022). "The activation of an ERK/JNK/P38 MAPK inflammatory pathway by IL-10 appears to enhance the progression of chronic pancreatitis to pancreatic cancer." (PMID 36339551, 2022). "According to a number of studies, an increase in IL-10 levels can dramatically drive tumor proliferation, metastasis, and immune evasion in a range of tumor models, including pancreatic cancer, and hence result in diverse pathologies." (PMID 36339551, 2022). "Our studies demonstrated that paeoniflorin dose-dependently inhibits IL-10 expression in pancreatic cancer cells." (PMID 36339551, 2022). "IL-1β, IL-6, IL-8, IL-10, TGF, and VEGF are PDAC-associated cytokines studied in duplicate in more than four studies, and are elevated in pancreatic cancer." (PMID 35159120, 2022). "The role of IL-10 in combination therapy in our study is consistent with the study in which IL-10 is armed in an oncolytic vaccinia virus for treating pancreatic cancer." (PMID 33717103, 2021). "Another pancreatic cancer clinical trial suggested that IL-10 combined with FOLFOX (Leucovorin, 5-FU, and Eloxatin) has no survival benefits." (PMID 33912464, 2021). "PI3K-γ expression in myeloid cells in murine pancreatic cancer models is associated with transcription of genes associated with the M2-macrophage phenotype in pancreatic cancer, including immunosuppressive factors like Arg1, TGF-beta, and IL-10." (PMID 34512641, 2021). "EV-miR-301a from hypoxic pancreatic cancer cells induces the M2 polarization of macrophages by targeting PTEN, which in turn promotes the migration, invasion, EMT and lung metastasis of pancreatic cancer cells probably by secreting IL10, TGF-β and arginase-1." (PMID 32503543, 2020). "For this, we first assessed possibility of IL10 modified mesenchymal stem cells for pancreatic cancer." (PMID 32742480, 2020). "This study also shows that it is feasible to transduce IL10 gene into MSC, which lays a foundation for the clinical application of IL10 to anti-angiogenic gene therapy in pancreatic cancer." (PMID 32742480, 2020). "At present, several experimental studies report promising results of IL10 which can significantly inhibit tumor growth and metastasis in a variety of tumor models including pancreatic cancer 26-28." (PMID 32742480, 2020). "In the current study, we evaluate the potential of using genetically modified MSCs which express IL10 constitutively to impede the pancreatic cancer cells proliferation in vitro and reduce the growth of tumor xenograft in vivo." (PMID 32742480, 2020).
pancreatic cancer (continued). "On the other hand, high secretion of IL-10 has been found in various types of cancer cell, including breast, kidney, colon, lung and pancreas cancer." (PMID 30947706, 2019). "Factors in the pancreatic cancer microenvironment, such as CSF-1, IL-4, IL-13, TGFβ and IL-10, can promote myeloid progenitor cell differentiation into monocytes and macrophages and recruit them to the tumor microenvironment." (PMID 30060755, 2018). "Immunosuppressive cytokines such as interleukin (IL)-10 and TGFβ are also secreted during pancreatic cancer to help fibrosis, immunosuppressive phenotype formation and recruit cells involved in immune evasion to overcome the anti-tumor immunity." (PMID 30060755, 2018). "Some of the proteins, such as IL10, ID1 and IL2, had been implicated as possible biomarkers of pancreatic cancer before." (PMID 28060763, 2017). "OC-expanded oral cancer patients’ NK cells secreted significantly less IL-10 when compared to healthy NK cells, whereas those from pancreatic cancer patients secreted higher IL-10 when compared to healthy NK cells." (PMID 28424683, 2017). "M2-polarized TAMs promote EMT in pancreatic cancer cells through Toll-like receptor 4 (TLR4)/interleukin-10 (IL-10) signaling." (PMID 28423676, 2017). "Second, FOXP3, the master transcription factor for Tregs, and its effective cytokine IL10, were associated with PDL1 upregulation in pancreatic cancers." (PMID 27589570, 2016). "Since IL-10 levels were significantly elevated in the circulation of pancreatic cancer patients compared to the controls, we tested the influence of IL-10 blockade on the ability of MSLN-specific T cells to produce IFN-γ." (PMID 24520352, 2014). "PBMCs from 7 patients with pancreatic cancer and 2 patients with benign pancreatic disease were peptide-stimulated in the presence of anti-IL-10 and anti-IL-10 receptor blocking antibodies (added to the cultures on day 1 and 4)." (PMID 24520352, 2014). "We found that there were higher levels of IL-6, IL-8, IL-10 and TNFα in patients with pancreatic cancer compared to healthy controls (for all, at least p<0.03)." (PMID 24849506, 2014). "We found that, among all analyzed cytokines, only IL-6, IL-8, IL-10, and IL-23 levels significantly differed between patients with pancreatic cancer and other individuals." (PMID 24849506, 2014). "As we observed significantly increased circulating IL-10 levels in pancreatic cancer patients, compared to the controls, here, we assessed the influence of IL-10 blockade on MSLN-specific T cell responses in 9 pancreatic disease patients." (PMID 24520352, 2014). "As we only collected the plasma samples on a single time point, we are not able to describe the change of plasma levels of MSLN and IL-10 during the progression of pancreatic cancer based on our data." (PMID 24520352, 2014). "Current reports state that circulating IL-10 levels were increased in pancreatic carcinoma compared to healthy controls." (PMID 24520352, 2014). "Here, we demonstrate that the plasma levels of Mesothelin and IL-10 are significantly increased in patients with pancreatic carcinoma." (PMID 24520352, 2014). "Our findings further show that, in addition to VEGF, CEC levels are strongly associated with the expression levels of IL-8, IL-10, and HGF in pancreatic carcinoma patients." (PMID 22731825, 2012). "Cyclin E1, epithelial growth factor (EGF), IL-6, CXCL8, IL-10, and IL-1RA have all been shown to be elevated in individuals with pancreatic cancer and high IL-6 or IL-10 levels correlated to poor survival." (PMID 20214814, 2010). "Therefore, IL-10-armed OVV shows promise as a novel treatment for pancreatic cancer by enhancing tumor inhibition through the regulation of innate and adaptive immune responses." (PMID 40469178, 2025).